IDH1 (isocitrate dehydrogenase (NADP(+)) 1)
Diseases named in the same sentence as IDH1 in open-access papers (continued):
Sharing a sentence is not in itself a finding about the gene and the disease.
glioma (continued). "We analyzed the maximum TBF and identified significant differences in the TBF in gliomas with different IDH1 statuses in Grade 1–4, Grade 3–4, and Grade 4 glioma groups." (PMID 35741254, 2022). "Our investigation focused on IDH1‐mutant gliomas because they have been traditionally described as being more vulnerable to oxidative stress." (PMID 34856072, 2022). "In the Cox proportional hazard multivariate regression model, only preoperative KPS (p = 0.006) and WHO 2016 grade II (p = 0.009) and III (p = 0.021) IDH1/2 mut gliomas confirmed a statistical correlation with the overall PFS and OS." (PMID 36176387, 2022). "For example, we identified increased levels of sarcosine, o-acetylcholine, and glutamate in IDH1-WT glioma compared with IDH1-mut glioma." (PMID 34941573, 2022). "The currently recruiting NOA-21 trial (NCT03893903) aims to assess safety and efficacy of combining IDH1-vac with the programmed death-ligand 1 (PD-L1) inhibitor Avelumab in recurrent glioma." (PMID 35158978, 2022). "In this study, we analyzed the outcomes of patients with IDH1/2 mutant grade 2 and 3 gliomas treated with LITT at a single institution." (PMID 35448183, 2022). "One hundred and eighty-three patients who had a histological sample taken had also truly IDH1 wild-type gliomas." (PMID 35371528, 2022). "Mutations in IDH1 and IDH2 are among the most well-studied metabolic disturbances in gliomas, including GB." (PMID 35806212, 2022). "IDH1-R132H suppresses tumor growth in gliomas via epigenetically activating the DNA damage response." (PMID 36276147, 2022). "The objective of this study was to characterize a single institution’s cohort of IDH1/2 mutant grade 2/3 glioma patients treated with LITT." (PMID 35448183, 2022). "In the current study, we described the correlation of EZH2 with IDH1 R132H protein mutant status in various grades of gliomas." (PMID 36292072, 2022). "The radiomics model based on multiparametric MR imaging from multiregional features showed the potential for preoperative detection of IDH1 status in glioma patients." (PMID 36290819, 2022). "Molecular biomarkers, such as IDH1/IDH2 mutations and 1p19q co-deletion, are included in the histopathological and clinical criteria currently used to diagnose and classify gliomas." (PMID 36360312, 2022). "As a result, gliomas with mutant IDH1 manifest a CpG island methylator phenotype (CIMP), which epigenetically alters gene expression by DNA hypermethylation." (PMID 35488886, 2022). "The analysis reveals that a higher expression of miR-181a is significantly associated with younger age of patients (<54-year, p = 0.006), lower tumor malignancy grade (p = 0.036), and gliomas with a mutant-type of IDH1 (p = 0.002)." (PMID 36232448, 2022). "Preliminary results of the first-in-human, multicenter, phase I study (NCT03030066) investigating the safety of DS-1001b in 45 patients with a diagnosis of recurrent/progressive IDH1-mut glioma were presented at the ASCO annual meeting 2019." (PMID 35267433, 2022). "TBF and normalized TBF (nTBF) in wildtype gliomas were significantly higher than in IDH1-mutant gliomas (p < 0.001)." (PMID 35741254, 2022). "In the subgroup of IDH1-mutant high-grade gliomas (n = 30), the values of maximum TBF were 110.24 ± 81.90 mL/100 g/min, normalized values were 6.13 ± 4.90." (PMID 35741254, 2022). "In particular, Cdkn2a+/+ mice with IDH1-mutant glioma had significantly longer median survival; however, they completely lost the survival advantage—and indeed faced a greater reduction in median survival—upon genetic deletion." (PMID 35203456, 2022).
glioma (continued). "GBMLGG data was segregated based on IDH1/2 status, with IDHmut gliomas further stratified between astrocytomas (1p/19q intact) and oligodendrogliomas (1p-19q codeleted), and overall survival plotted based on median BET isoform (BRD2/3/4) expression levels." (PMID 35467128, 2022). "Radiotherapy was applied to the intracranial IDH1 mutant glioma model in 2 consecutive weeks at 3 Gy per dose, 2 days per week." (PMID 36353533, 2022). "What’s more, the IDH1/2 mutant type has a better prognosis than the IDH1/2 wild type in glioma with the same pathological grades." (PMID 35747806, 2022). "The G-CIMP profile is tightly associated with IDH1/2 mutations and better outcomes for patients with IDH-mutated gliomas." (PMID 36092918, 2022). "Mutations in IDH1/2 occur frequently in acute myeloid leukemia (AML) and gliomas and are neomorphic mutations that lead to the aberrant production of 2-hydroxyglutarate (2-HG) while consuming NADPH." (PMID 35426374, 2022). "The following eight explanatory variables were used: age, sex, Karnofsky performance status (KPS), location of the glioma, tumor diameter, pathological grade, isocitrate dehydrogenase (IDH)-1-R132H status, and Ki-67 index." (PMID 36514578, 2022). "Both groups showed similar levels of tricarboxylic acid (TCA) cycle intermediates, but IDH1 mutant gliomas accumulated more pyruvate." (PMID 36698888, 2022). "Classifying gliomas based on recurrent IDH1 point mutations, which have been linked to gliomagenesis, is important because it distinguishes mutant IDH1 gliomas from wild-type-IDH1 (wt-IDH1) gliomas." (PMID 36276147, 2022). "DNA methylation patterns were associated with the mutations in IDH1 or IDH2 in lower grade gliomas, and mutations in histone 3 in pediatric high‐grade gliomas." (PMID 35338570, 2022). "Other genes and gene products with smaller alterations, such as mutant IDH1 protein, were detected in glioma patient sera and cerebrospinal fluid extracellular vesicles." (PMID 35806478, 2022). "Interrogation of cancer genomic databases and a systematic review was undertaken, demonstrating the rarity of the co-occurrence of IDH1 and IDH2 mutations in a variety of cancer types, and in glioma specifically." (PMID 36286062, 2022). "There have obtained many identifications about some phenotypes of glioma which are useful to prognosis, such as methylation of the MGMT, mutations in IDH1/2 and so on." (PMID 35931979, 2022). "Accurate detection of IDH1/IDH2 mutation and 1p19q co-deletion status is important for appropriate tumor classification of gliomas under the most recent 2021 WHO classification of central nervous tumors." (PMID 36360312, 2022). "Neomorphic mutations in isocitrate dehydrogenase (IDH) enzymes (arginine 132 for IDH1 and arginine 172 for IDH2) are found in 70% of gliomas and are highly associated with favorable outcomes of glioma patients." (PMID 35216362, 2022). "The LGG cases under study were classified into four groups based on genetic characteristics agreeing with WHO 2021 stratification of gliomas: The IDH-wt group collects unmutated (wild type) IDH1 and/or IDH2 (IDH) gliomas." (PMID 35681780, 2022). "Our median duration of follow-up was shorter than prior literature analyzing outcomes in IDH1/2 mutant gliomas after surgical resection, although our median approached the recommended threshold for IDH1/2 mutant gliomas." (PMID 35448183, 2022). "The DNA methyltransferase inhibitor 5-azacytidine has been shown to reduce methylation, promote differentiation and, finally, induce tumor regression in a patient-derived IDH1 mutant glioma xenograft animal model." (PMID 35806153, 2022). "Mutant IDH1 (IDH1-mut) glioma cells downregulate ICAM1 via ICAM1 promoter methylation resulting in an increased expression of LAMP1 (CD107a), a lysosome-associated membrane protein which has a key role in the formation of phagolysosomes (Molecular event 24)." (PMID 36555253, 2022).
glioma (continued). "The current case series represents the first of its kind to analyze treatment outcomes in IDH1/2 mutant glioma in particular." (PMID 35448183, 2022). "More and more studies have proved that the molecular typing of glioma plays an irreplaceable role in its development, such as IDH1." (PMID 35350840, 2022). "Ivosidenib is the first and only IDH small molecule inhibitor that is currently under clinical investigation in combination with immunotherapy in IDH1 mutant tumors, including gliomas." (PMID 36303101, 2022). "The present research suggests that IDH1 mutation, 1p19q LOH, EGFR mutation and MGMT promoter methylation are newly added major molecular markers for genetic molecular typing of glioma." (PMID 36181110, 2022). "In summary, we showed that our deep learning-based framework can detect and segment gliomas with excellent performance and can provide high prediction accuracy for IDH-1 and modest accuracy for MGMT." (PMID 36139616, 2022). "Mutant IDH1 promotes glioma growth in cells with PDGFA amplification and/or inactivation of CDKN2A, ATRX and PTEN." (PMID 35382567, 2022). "In routine clinical diagnostic practice, the presence of positive immunohistochemical staining for IDH1 R132H within a glioma obviates the need to sequence IDH1 or IDH2, as the clinically relevant mutation has been identified." (PMID 36286062, 2022). "The IDH1 (R132H) mutation is shared among more than 70% of diffuse grade II and III gliomas and serves as a shared neoantigen." (PMID 35651800, 2022). "These same IDH1 and IDH2 variants have been reported in many cancers such as acute myeloid leukemia (AML) and glioma where co-occurrence with variants in other genes is a common mechanism." (PMID 36480544, 2022). "In IDH1 R132H-negative gliomas, there was a trend toward shorter 5-year PFS (mean = 8.0 months, p = 0.001) and 5-year OS (mean = 28.7 months, p = 0.06) in gliomas demonstrating high EZH2 expression compared with those with low EZH2 expression." (PMID 36292072, 2022). "Recent studies reported that the IDH1 mutant glioma tissue displayed massive alterations in glycolysis and lipid metabolism compared with IDH1 wild-type glioma tissue." (PMID 36698888, 2022). "This study supports the notion that IDH1 mutant and IDH1 wildtype gliomas have different epigenetic landscapes and that accessible chromatin sites mapped by atac-seq peaks tend to be positively correlated with expression." (PMID 35581287, 2022). "In our study, two IDH1 mutant gliomas were located in the frontal, and one in the temporal lobe, all three with above median ascorbate content." (PMID 35419292, 2022). "The expression of the Rac1 mRNA in low-grade gliomas (LGG, with IDH1 mutated) and GBM was analyzed using the GTEx and TCGA databases." (PMID 36230732, 2022). "We performed methylome profiling of glioma tissues (GBM WHO IV) and the primary GBM cells derived from the tissues were characterized for the mutational status of IDH1/IDH2 and methylation of MGMT as described in Materials and Methods." (PMID 35393392, 2022). "Noninvasive detection of glutamate by magnetic resonance spectroscopy can serve as a metabolic imaging biomarker of response to temozolomide treatment in IDH1-mut glioma." (PMID 34941573, 2022). "Although patients with IDH1 mutant and 1p/19q co-deleted glioma tumours exhibit improved survival and outcome, many eventually develop resistance and refractory glioma." (PMID 36120909, 2022). "In 2016, the World Health Organisation (WHO) adopted isocitrate dehydrogenase 1 (IDH1) and isocitrate dehydrogenase 2 (IDH2) single nucleotide variants (SNVs) into its classification of gliomas." (PMID 36286062, 2022).
glioma (continued). "Analysis of high-grade gliomas with different IDH1 statuses found significant differences in blood flow." (PMID 35741254, 2022). "Mutations in IDH1/2 and the epigenetic silencing of TET2 occur in leukaemia or glioma in a mutually exclusive manner." (PMID 34905094, 2022). "IDH1 R132 or IDH2 R172 mutant gliomas usually arise in a younger patient population, and patients with low grade gliomas (LGG) typically have a long overall survival time (5–10 years)." (PMID 35216362, 2022). "Mutations to IDH1/2 are important events in several types of cancers, including acute myeloid leukemia (AML), glioma, angio-immunoblastic T-cell lymphoma, chondrosarcoma, intrahepatic cholangiocarcinoma, and so on." (PMID 35814406, 2022). "The aim of our research was to study the relationship between tumor blood flow (TBF) measured by the PCASL method and the IDH1 status of gliomas, as well as the Ki-67 index." (PMID 35741254, 2022). "Subgroup analysis of HGG (Grade 3–4) and glioblastomas (Grade 4) with different IDH1 statuses also demonstrated that wildtype gliomas from these subgroups had higher TBF values." (PMID 35741254, 2022). "Due to the histopathological heterogeneity of glioma, the TAF12 mRNA expression data were analyzed according to WHO grade, histology, IDH1 mutation, and other features." (PMID 36551275, 2022). "And GPX8 expression is significantly correlated with grade, IDH1/2 mutation, and 1p/19q codeletion in primary glioma from CGGA, which are favorable prognostic factors in glioma." (PMID 36052280, 2022). "Mutations of IDH1 and IDH2 were found in >70% of lower-grade gliomas and some IDH-mutated high-grade gliomas." (PMID 36295820, 2022). "The IDH1 pan-inhibitor BAY-1436032 slowed in vitro proliferation of primary glioma cultures, inducing their differentiation, with the astrocytic marker GFAP upregulated upon treatment." (PMID 35267433, 2022). "The detection and reporting of alterations such as IDH1/2 mutation, 1p/19q co-deletion, EGFR amplification, TERT-promoter mutation, and CDKN2A homozygous loss in the diagnosis of infiltrating glioma has become standard practice in clinical neuropathology." (PMID 36397144, 2022). "There are three isoforms of the IDH gene, of which the most important in gliomas are cytosolic IDH1 and mitochondrial IDH2 mutations; most IDH-mutated gliomas harbor IDH1 mutations in the form of IDH (R132H)." (PMID 35693015, 2022). "These phenomena are coincident with the consensus that mutations in IDH1 and ATRX are the initiating events for the development of many gliomas, and their presence dictates favourable clinical behaviour." (PMID 35194922, 2022). "These trends are also illustrated in three representative cases of IDH1-mutant glioma patients with differential responses to IDH inhibition." (PMID 36033919, 2022). "We observed that collagen fibers were aligned within oncostreams and overexpressed in more aggressive NPA (IDH1-WT) gliomas compared with NPAI (IDH1-Mut) tumors." (PMID 35750880, 2022). "In a grade III IDH1-mut orthotopic patient-derived xenograft TS603 glioma model, vorasidenib treatment led to a >97% inhibition of 2-HG production in mice brains at doses ≥0.1 mg/kg." (PMID 35267433, 2022). "IDH1, CIC, and NF1 have been repetitively reported in gliomas and the preferential distribution of IDH1 in the LGG group verified the clinical classification of our patient cohort." (PMID 35865002, 2022). "Antibody-mediated blockade of CXCR3, CXCL10’s cognate receptor, also reduces CD8+ T cell chemotaxis toward the supernatant of CXCL10-containing IDH1-WT glioma cells by roughly 3.5-fold." (PMID 35385679, 2022).
glioma (continued). "Between February 2017 and July 2018, ten patients were enrolled, six with IDH1-mutant and four with IDH1 wild-type gliomas." (PMID 35740557, 2022). "In this study, we evaluated the use of a DNA methylation array to simultaneously identify the two most important biomarkers of glioma: IDH1/IDH2 status and 1p19q co-deletion." (PMID 36360312, 2022). "The oncometabolite 2-hydroxyglutarate, produced by mutant IDH1 and IDH2-encoding enzymes, influences TAM composition in high-grade gliomas." (PMID 35513201, 2022). "Mutant IDH1 was shown to promote the glioma cytosine–phosphate–guanine (CpG) island methylator phenotype (G-CIMP) in gliomas, which are often characterized by the epigenetic silencing of MGMT." (PMID 36361838, 2022). "This includes IDH1/2 in gliomas and acute myeloid leukaemia (AML), SDH in PGLs and FH in HLRCC due to the production of oncometabolites, D-2-HG, succinate and fumarate." (PMID 35382567, 2022). "Considering that IDH co-occurring mutations in different IDH1 loci or in IDH1 and IDH2 loci are extremely rare events in gliomas, our finding is of special interest to the field." (PMID 35740557, 2022). "IDH1/2 mutation had better response to temozolomide (TMZ) and were associated with the prognosis of glioma patients." (PMID 35227235, 2022). "In contrast to low-grade gliomas (LGG), WHO grade 4 wt-IDH1 high-grade gliomas exhibit more somatic mutations and multiple genomic alterations." (PMID 36276147, 2022). "Two recent studies revealed that IDH1-mutant glioma cells are hypersensitive to drugs targeting enzymes in the de novo pyrimidine nucleotide synthesis pathway." (PMID 36568190, 2022). "Such a difference was also observed in our study, which is the first to identify a statistically significant correlation between the proliferative index of grade 4 gliomas, depending on the status of the IDH1 gene." (PMID 36136867, 2022). "Other studies of IDH1 and IDH2 mutations in gliomas point to them as having distinct mutational and clinical patterns." (PMID 36042521, 2022). "IDH1 is increasingly recognized as an independent prognostic marker for gliomas, consistent with our findings." (PMID 36245971, 2022). "A comparison of blood flow in groups of Grade 2–3 gliomas with different IDH1 statuses revealed that wildtype gliomas had higher rates of TBF (p = 0.029) and nTBF (p = 0.065)." (PMID 35741254, 2022). "Recently, mutations in the enzyme cytosolic isocitrate dehydrogenase (IDH1) were discovered to inhibit STAT1 signaling to induce CD8+ T cell accumulation, thereby promoting immune evasion in gliomas." (PMID 35222387, 2022). "Due to its high specificity, 2HG is a valuable imaging biomarker for diagnosing, monitoring, assessing tumor burden, treatment response, and pharmacodynamics of targeted therapy in mutant IDH1 glioma." (PMID 35911635, 2022). "The new WHO (World Health Organization) classification distinguishes between IDH1/2 (isocytrate dehydrogenase 1/2) mutant gliomas, which include lower-grade gliomas (LGGs) (grade 2–3) and grade 4 IDH1/2 mut gliomas, and IDH1/2 wild-type glioblastomas (GBMs)." (PMID 36325374, 2022). "NPA (IDH1-WT) tumors exhibited larger areas of oncostreams within a highly infiltrative and heterogeneous glioma characterized by abundant necrosis, microvascular proliferation, pseudopalisades and cellular heterogeneity." (PMID 35750880, 2022). "Various somatic point mutations of IDH1 or IDH2 have been discovered in a variety of malignancies in recent years, such as gliomas and AMLs (acute myeloid leukemias)." (PMID 36188571, 2022). "In cohorts treated primarily by surgical resection and adjuvant therapy, median PFS for IDH1/2 mutant grade 2 and 3 gliomas ranged from 46.8 to 78.0 months." (PMID 35448183, 2022).